RAF1 (Raf-1 proto-oncogene, serine/threonine kinase)
Diseases named in the same sentence as RAF1 in open-access papers (continued):
Sharing a sentence is not in itself a finding about the gene and the disease.
cancer (337 papers, 1998 to 2025). A tumor composed of atypical neoplastic, often pleomorphic cells that invade other tissues. "Huang and colleagues conducted a comprehensive study of RAF1 and its interactions with other proteins, revealing that RAF1 interacts with 198 proteins involved in various signaling pathways and biological processes, including those associated with cancer." (PMID 40727567, 2025). "In this study, we wanted to know how RAP1A SNPs affected its interaction with RAF1 and their role in cancer susceptibility and development." (PMID 39498560, 2025). "In cancer patients, abnormal and aberrant RAF1 activation is associated with tumor growth and the development of therapy resistance." (PMID 39498560, 2025). "For example, elevated 5hmC levels in MAPKs like MAPK1 and RAF1 were significantly associated with shorter OS, consistent with their recognized oncogenic roles in cancer." (PMID 38391911, 2024). "The RAS (KRAS, NRAS, HRAS)-RAF (ARAF, BRAF, RAF1)-MEK (MAP2K1/2)-ERK (MAPK1/3) pathway is altered in ~40% of all human cancers, mainly through oncogenic mutations in RAS (32%) and the downstream effector BRAF (~10%)." (PMID 37370689, 2023). "Overall, developing methods for treating RAF1 mutant variants represent promising therapeutic targets in multiple cancer types." (PMID 38111008, 2023). "Raf-1 upregulation is essential for erythroid development and is also implicated in certain cancers, including leukemia, squamous cell carcinoma, ovarian cancer, and melanoma." (PMID 38136612, 2023). "In agreement with this notion, RAF1 mutations were detected in about 0.7% of human cancer cell lines." (PMID 35203304, 2022). "Although mutations of Raf-1 are much rarer in cancer than B-Raf, several studies have reported germline mutations of C-Raf in human diseases." (PMID 35563547, 2022). "The frequency of activating RAF1 mutations in human cancers is much lower, because RAF1 has a lower basal kinase activity than BRAF." (PMID 35203304, 2022). "RKIP mediates its suppressive action in the constitutive activation of several cancer progression-associated signaling pathways including the Raf-1/MEK/ERK, G-protein coupled receptor (GPCR) and NF-κB pathways." (PMID 36230521, 2022). "RAF1 (also known as CRAF) mutations are less prevalent (about 2%) although multiple studies have found elevated RAF1 expression in a range of primary human cancers." (PMID 34692523, 2021). "For example, rapamycin has been shown to rescue cellular and behavioral phenotypes in mouse knockouts of PTEN52, while sorafenib inhibits growth and promotes apoptosis in cancer cells with RAF1 mutations." (PMID 29959322, 2018). "GnrH receptors and the associated Raf-1/MEK/ERK-1/2-pathway are potential targets for analogs in cancer treatment." (PMID 22269186, 2012). "In fact, even kinase-dead BRAF mutations, which have been observed in human cancer, the mutant B-Raf proteins can dimerize with Raf-1, when stimulated by the mutant Ras protein and activate the Raf/MEK/ERK cascade." (PMID 23085539, 2012). "Nevertheless, several types of human cancers show activating RAF1 mutations." (PMID 35203304, 2022). "Upon binding to Raf-1 sorafenib may cause disarray in Raf-1 dependent pathways, which are known to play a role in survival signaling mechanisms for cancer cells including MEK/ERK, MST-1, and ASK-1." (PMID 34639131, 2021). "In addition, Ccnd2, Ccnd1, and Raf1 are targets of the downregulated miR-15b-5p in exposed mice, and these targets are implicated in cancer and cell cycle regulation." (PMID 34199666, 2021). "Raf-1 kinase feedback regulation might be associated with radiotherapy sensitivity by enhancing its antiapoptotic function in cancer cells." (PMID 32963532, 2020).
cancer (continued). "RAF-1 has been found to be associated with different cancers, especially colorectal cancer (CRC)." (PMID 29118938, 2017). "Different studies have shown that activation of RAF-1 is strongly associated with resistance to apoptosis which might be the major cause of uncontrolled cell cycle divisions in cancer." (PMID 29118938, 2017). "Polymorphism of miRNAs has an impact on alternation of cancer-related genes, such as RAF-1, that could determine probable susceptibility to cancer." (PMID 29118938, 2017). "In the previous study, RKIP can inhibit the radiation resistance of cancer caused by Raf-1." (PMID 27647315, 2016). "While the activation of Raf-1 requires a complex series of events, the activation of B-Raf is much simpler to achieve, explaining why B-Raf is a preferred target for mutational activation in human cancers." (PMID 14735164, 2004). "Similarly, Renca cells showed dynamic expression changes of multiple genes across passages, including Btbd17, Loxl3, Raf1, and Acvrl1, which may be closely associated with signal transduction, transcriptional regulation, and cancer-related pathways." (PMID 41272245, 2025). "In addition, miR‐7 could target numerous oncogenic genes in cancer‐associated pathways, such as EGFR,37PIK3CD,38Ack139 and Raf1,40 indicating the significant suppressive roles in cancers." (PMID 34551195, 2021). "A broad panel of functional analysis indicated that Damnacanthus indicus C.F.Gaertn-related genes are predominantly cancer-associated and may have a functional association with the Raf1 pathway, thereby, suggesting the relationship of the Damnacanthus indicus C.F.Gaertn DPT with the Rap1 pathway." (PMID 30906409, 2019). "Combining natural selection, gene-based pathway analysis, and other associated analysis, we proposed that the pathway was significantly associated with PCa risk, in which the mutation of EGFR, ERBB2, PTK2, RAF1, and related SNPs in the genes might be the key link in the evolution of the cancer." (PMID 24223781, 2013). "Thus mutation at both BRAF and CRAF have been detected in certain cancer patients and other studies have shown that the levels of mutant and WT B-Raf, Raf-1 and RKIP will influence the levels of transformation observed, hence there is a strong basis for the development of Raf inhibitors." (PMID 21422497, 2011). "Survival analysis results revealed a strong association between RAF1 and RAP1A expression levels and diminished survival rates in cancer patients across different cancer types." (PMID 39498560, 2025). "The high degree of interaction observed in genes like MAPK3, MAP3K1, SRC, and RAF1 further supports their roles in regulating cellular signaling, which is crucial for understanding cancer biology and therapeutic resistance." (PMID 40136517, 2025). "YM-1 exhibits anticancer activity by destabilizing oncoproteins such as Akt and Raf-1, demonstrating efficacy against various cancer cell lines with similar EC50 values, e.g., tamoxifen-resistant MCF7 breast cancer cells." (PMID 41425251, 2025). "Cancer cells with RET/PTC1 rearrangements rely more on the RAF‐1 pathway for survival and growth than on the BRAF‐ERK pathway, which is typically needed in cells with RAS or BRAF mutations." (PMID 40911853, 2025). "Through predictive algorithms and molecular simulations, we identified deleterious mutations in RAF1 and RAP1A, shedding light on their impact on cancer patient survival." (PMID 39498560, 2025). "This adds a new dimension to our understanding of Raf1's physiological functions beyond its well-characterized role in cancer biology." (PMID 40432214, 2025).
cancer (continued). "In various cancer types RKIP functions as a direct suppressor of key signaling pathways including Raf-1/Mek/Erk, NF-κB, STAT3, GSK3β, and GPCRs signaling." (PMID 40806276, 2025). "RAF1 plays a pivotal role in RAS-driven cancers as it is the continuous activation of RAF1 kinase by constitutively active oncogenic RAS proteins that drives many cancers." (PMID 39049057, 2024). "Sorafenib can interfere the transduction of extracellular-signal-regulated kinase (ERK) signaling and inhibit cancer cell proliferation through downregulating the expression of the isoforms of serine/threonine kinases Raf, Raf-1, and B-Raf." (PMID 38596684, 2024). "RAF1, also known as CRAF, belongs to the same family as BRAF and participates in the MAPK signaling pathway and is associated with various cancers including melanoma." (PMID 38470950, 2024). "It is widely accepted that the RAF1/MEK1/ERK signaling pathway is one of the most commonly dysregulated pathways involved in cancer development." (PMID 39076089, 2024). "It is noteworthy to highlight that, Raf-1 is a critical component of the MAPK signaling cascade aberrantly activated in cancer cells." (PMID 39564119, 2024). "From a mechanistic perspective, RNF115 activated the Raf-1 pathway and enhanced cancer cell cycle progression by degrading CDK10 in THCA cells." (PMID 38376606, 2024). "Activating mutations of the genes encoding the kinases BRAF, RAF1, MAP2K1 and 2 and MAPK1/3 are also known cancer drivers." (PMID 39436906, 2024). "On the other hand, overexpression of RAF1 promotes cancer progression while its knockdown with siRNAs results in apoptosis, interferes with cytoskeletal activity, and dysregulates proliferation." (PMID 39436906, 2024). "In cancer research, Raf-1 and Akt can interact with STK3 kinases to inhibit STK3 dimerization with RASSF1A, thus promoting cell proliferation, transformation, and survival." (PMID 38436783, 2024). "There are four residues of RAF1 and thirteen residues of BRAF related to cancer mutations at the interface of BRAF–RAF1 complex." (PMID 38216592, 2024). "After ERK is activated by mitogenic stress or conditional active Raf-1 and MEK, phosphorylated ERK translocates to the nucleus and promotes the transcription of genes associated with cancer progression." (PMID 36639650, 2023). "Nevertheless, oncogenic mutant RAF1 remains a rare target for the deployment of selective CRAF inhibitors in RAF or RAS-driven cancers." (PMID 38111008, 2023). "Studies have verified that RAF1 is carcinogenic in various cancers, but it has also been proven to be a cancer-inhibiting gene in hepatocarcinogenesis." (PMID 36769510, 2023). "The frequency of MSI-H tumors was significantly higher in patients with RAF1 aberrations compared to those with RAF1 wild-type cancers (6.6% vs. 2.1%, p < 0.0001)." (PMID 38137485, 2023). "The interplay between MEK1 and CRAF rather than A/B-RAF is reminiscent of the well-defined scenario in RAS-driven cancer that CRAF (RAF1) transduces signals from RTKs to MEK." (PMID 36765038, 2023). "One of the most striking findings of these experiments is that the expression of endogenous R-RAS2Q72L is required for cancer cells that harbor concurrent mutations in key signaling elements of the RAS route, such as BRAF, RAF1 and PI3Kα." (PMID 36476833, 2023). "The remaining two paralogs, ARAF and RAF1 (also known as CRAF) are less potent activators of MEK, and are rarely mutated in human cancers." (PMID 37079639, 2023). "A mechanism has been described in which EZH2 expression-mediated downregulation of DNA damage repair leads to accumulation of recurrent RAF1 gene amplification in Cancer Initiated Cells (CIC), which activates p-ERK-β-catenin signaling and enhanced CIC growth." (PMID 35955891, 2022). "Among these, six cancers had additional genetic alterations: BRAF fusions (n = 2), and one each with RET fusion plus BRCA2 loss of function mutation, IDH1 mutation, RAF1 fusion, and EML4-NTRK3 fusion." (PMID 36124727, 2022).
cancer (continued). "We assume that this protein-protein interaction increases the capability of cancer cells to desaturate toxic saturated fatty acids, highlighting Raf-1 as an important regulator of lipid metabolism in cancer." (PMID 34302061, 2021). "The aberrant mitogenic signaling in Ras-driven cancer cells largely depends on the increased recruitment of the downstream effectors Raf1, from the constitutively active Ras oncoproteins." (PMID 33681292, 2021). "Activated KRAS binds and activates RAF family kinases (RAF1, BRAF, and ARAF), subsequently leading to uncontrolled proliferation and other processes causing cancer development and spread." (PMID 35141142, 2021). "Together, these findings suggest that PHB1 phosphorylated at T258 by Akt can increase the invasiveness of cancer by direct interaction with Raf-1." (PMID 34868199, 2021). "PHB1 interacts with CRaf (Raf-1), which can activate pathways involving Ras that support cancer and its invasiveness, such as the CRaf/ERK, PI3K/Akt, and RalGEF/Ral pathways." (PMID 34868199, 2021). "Previous studies have indicated that RIPK4 can activate the NF-κB pathway and RAF1/MEK/ERK signalling in cancer oncogenesis and development." (PMID 33855091, 2021). "One of the Kras signalling pathways for cancer growth is mediated by its downstream molecule, Raf1, via the interaction of the Ras-binding domain (RBD) of Raf1 (Raf1-RBD) and activated Kras; Y13-259 whole IgG interferes with this interaction." (PMID 31953402, 2020). "The classic Raf/MEK/ERK (extracellular signal‐regulated kinase) signalling is generally accepted as responsible for the function of Raf‐1 in cancer development, including in NSCLC." (PMID 31541523, 2019). "It is widely believed that Raf1/MEK1/ERK signaling pathway is one of the most commonly deregulated pathways in various cancer including ESCC." (PMID 30971268, 2019). "The Kirsten rat sarcoma viral oncogene homolog (RAS)/v-raf-1 murine leukemia viral oncogene homolog 1 (RAF)/mitogen-activated protein kinase 1 (MAPK) signaling cascade is the most important oncogenic pathway in human cancers." (PMID 31540406, 2019). "Consistent with this, KRAS proximity to EGFR and its canonical downstream kinases, Raf1 and PI3K P110α decreased with SNARE TKO and increased with SNORD50A/B KO in cancer cells with activating oncogenic KRAS mutations." (PMID 31712554, 2019). "MiR-7 targets and downregulates oncogenic factors in cancer-associated signaling pathways including EGF, Bcl-2, Raf1, and Akt/PI3K61." (PMID 30783079, 2019). "While B-Raf has the highest occurrence of mutations in human cancers and therefore appears to have a dominant role in the ERK signaling pathway, c-Raf, also known as Raf-1, has been the most extensively studied and thus is the best characterized Raf kinase." (PMID 30795516, 2019). "Rare and possibly damaging variants were identified in 12 candidate genes in this cohort, including variants in DNA repair genes (ERCC1 and SXL4) and other cancer-related genes (NOTCH2, ERBB2, MST1R, and RAF1)." (PMID 29868112, 2018). "Of the remaining 17 variants, all but three are accounted for by six genes (BRAF, CBL, MAP2K1, MAP2K2, RAF1, and SOS1) encoding members of the RAS-MAPK pathway, among which nine variants have previously been reported in either congenital disorders or cancer." (PMID 30355600, 2018). "Several activators of MEK/ERK1/2 in human cancers have been identified, such as RAF1, IGF-1R and Connexin-43." (PMID 30016974, 2018). "Our results indicate that melatonin holds considerable potential for use in the treatment of cancers exhibiting RAF1 overactivation." (PMID 30201903, 2018). "Accumulating evidences indicate that RAF1 is highly expressed in various malignant tumors, including HCC." (PMID 29506567, 2018). "Gene ontology (GO) and pathway enrichment analysis indicated that these Raf1-protein interactions regulated six signaling pathways, and were involved in the ten known hallmarks of cancer." (PMID 28978120, 2017).
cancer (continued). "After NMI knockdown, the expression levels of MAPK signaling pathway members, including Raf1, MAPK11, MAP3K14 and MAP3K2, which are associated with cancer invasion and metastasis, were obviously decreased HCC-LM3." (PMID 28077802, 2017). "These interaction partners were involved in all ten hallmarks of cancer, suggesting that Raf1 is involved in different aspects of carcinogenesis." (PMID 28978120, 2017). "Bcl-2-associated athanogene-1 exists as multiple protein isoforms that interact with diverse partners, including chaperones Hsc70/Hsp70, Ser/Thr kinase Raf-1 and Bcl-2, to promote cancer cell survival." (PMID 28510570, 2017). "Other researchers have shown that overexpression of ciRS-7 in cancer tissues permitted inhibition of miR-7 and subsequent activation of EGFR and RAF1 oncogenes, again, strengthening the argument that circRNAs play a role in cancer initiation and development." (PMID 28634583, 2017). "Pathways in Cancer describe of 251/327 genes RAF1 and VHL again as G1 nominators followed by WNT7A (15/26) and MLH1 (22/26) with p<0.00553, respectively p<0.00985." (PMID 28486536, 2017). "In cluster 2, the key genes CDKN2A, HSP90AB1, TRAF2 and RAF1 are effective agents in cancer pathway." (PMID 29379595, 2017). "The identified Raf1 interacting proteins were involved in all hallmarks of cancer, highlighting the importance of Raf1 in carcinogenesis." (PMID 28978120, 2017). "The lipid influences SUP-T1 cell aggressiveness since stimulates DNA and RNA synthesis for cell proliferation and increases raf1 and E-cadherin, molecules involved in invasion and migration of cancer cells." (PMID 26754536, 2016). "RKIP was initially identified as an inhibitor of the Raf/MEK/ERK pathway, which is necessary for growth and proliferation of cancer cells, via its direct interaction with Raf1." (PMID 26716415, 2016). "Understanding how such peptides bind and disrupt the dimerization process is key for future development of anti-cancer drugs that can activate MST2 by releasing it from the inhibitory interaction with RAF1." (PMID 27716844, 2016). "Then, we analyzed the behavior of raf1 and e-cadherin, as molecules involved in migration and/or invasion of cancer cell." (PMID 26754536, 2016). "The kinase RAF1 usually exerts pro-tumorigenic functions promoting proliferation in RAS-driven cancers." (PMID 28000790, 2016). "We have shown a correlation between hyperCHO and increase of DNA and RNA synthesis as well as raf1 and e-cadherin content, important molecules for cancer progression." (PMID 26754536, 2016). "Previous studies have demonstrated that Ras/Raf-1/ERK signaling plays a crucial role in EMT regulation in several cancers." (PMID 25326651, 2014). "The major function of Hsp90 is to maintain the stability and activity of multiple kinases, transcription factors and steroid receptors, many of which are dysregulated in human cancer, such as Raf-1, EGFR and AKT." (PMID 24662070, 2014). "It has been established that Raf-1 can promote the initiation, transformation and maintenance of neoplastic lesions in some cancer models." (PMID 25373319, 2014). "We illustrate the interface related affinity properties of two cancer-related hub proteins: Erbb3, a multi interface, and Raf1, a single interface hub." (PMID 20011507, 2009). "Here, we show in 12 human in vitro cancer cell lines that late G1 accumulation after 2 Gy of radiation is related to both Raf1 expression (r = 0.91, P = 0.0001) and the radiosensitivity parameter SF2 (r = -0.71, P = 0.009)." (PMID 9579826, 1998).